CTLA4 (cytotoxic T-lymphocyte associated protein 4)
Diseases named in the same sentence as CTLA4 in open-access papers (continued):
Sharing a sentence is not in itself a finding about the gene and the disease.
tumor (continued). "Specifically, the IM subtype exhibited a robust immune infiltration, along with a FI spatial distribution pattern, an increased density of CTLA-4+ and PD-1+ TILs, and high PD-L1 expression by tumor cells, indicative of “immune-hot” tumors." (PMID 38893213, 2024). "In mice, sodium butyrate inhibited the anti-CTLA-4-induced maturation of DCs and accumulation of tumor-specific T cells and memory T cells and diminished the antitumor effect of CTLA-4 blockade treatment." (PMID 39840031, 2024). "In recent years, immunotherapy has emerged as a promising therapeutic avenue for various cancers, with monoclonal antibodies targeting immune checkpoints, such as PD‐1 and CTLA‐4, demonstrating clinical efficacy across diverse tumor types." (PMID 38506237, 2024). "In this model, anti-CTLA4 therapy prevented tumor growth independently of the presence of PG/VG + 36 mg/mL nicotine." (PMID 39221247, 2024). "Macrophage depletion completely abrogated the enhanced protective benefits and the delay in tumor growth provided by IVAX to anti-CTLA-4 therapy." (PMID 38517331, 2024). "ICI efficacy relies on normal immune function, where ICIs inhibit receptors such as PD-1, PD-L1, and CTLA-4 on tumor cells, enhancing the ability of immune cells to attack tumors." (PMID 38935663, 2024). "KN046 emerges as a pioneering humanized bispecific antibody that dually targets PD-L1 and CTLA-4, which has demonstrated a remarkable capacity to potentiate the immune response specifically within the tumor." (PMID 39105827, 2024). "The blockade of CTLA-4 has been shown to promote the expansion of effector T cells and reduce the number of Tregs in the tumor microenvironment, further amplifying the antitumor immune response." (PMID 39335671, 2024). "Cytotoxic T-lymphocyte-associated protein 4 (CTLA-4) is a regulatory molecule that can inhibit the immune response and is related to tumor aggressiveness." (PMID 38978137, 2024). "Similar to PDCD1 and CTLA4, which were scattered across the tumor region with evident T cell aggregation, CXCL13-CXCR5 had a similar spatial distribution." (PMID 39256364, 2024). "A hallmark of T cells exhaustion is persistent expression of markers including Tox, Ctla4, Entpd1, Pdcd1, Havcr2, and others, many of which were expressed in the tumor TEX subset." (PMID 38496632, 2024). "Tregs, as one of the most important parts of immunosuppressive cells, can inhibit tumor-specific immune responses with the co-inhibitory molecules such as CTLA-4, TIGIT, LAG3, and CD28, and promote immune evasion, thus facilitating tumor cell proliferation." (PMID 38671348, 2024). "Studies have indicated that altered PD-1 and CTLA-4 gene expression in PBMCs correlates with tumor development, progression, and response to therapy." (PMID 38672574, 2024). "The authors found that TCM intervention significantly inhibits tumor growth and metastasis, possibly by inhibiting CTLA-4 in tumor tissues, reducing Treg cell numbers and function, improving immune tolerance, and inhibiting tumor growth and metastasis." (PMID 38792234, 2024). "The clinical trial results indicate that utilizing ipilimumab at 1 and 3 mg/kg dosages effectively interrupted CTLA-4 signaling, resulting in anti-tumor activity in patients with B cell lymphoma." (PMID 38191571, 2024). "On the other hand, the expression of tumour-specific MHC-I is required for responding to anti-CTLA4 therapy." (PMID 38893071, 2024). "Tregs infiltrating the tumour constitutively express CTLA-4, contributing to creating an immunosuppressive environment in cancer." (PMID 38893123, 2024). "TAM-derived IL-10 and TGF-β promote Treg differentiation and expansion, while Treg-mediated CTLA-4 expression and IL-10 release further dampen the anti-tumor immune response." (PMID 39450177, 2024). "Nevertheless, preclinical studies have shown that anti-CTLA-4 combination therapy can effectively control tumor growth in BC." (PMID 38956700, 2024).
tumor (continued). "In an EMT-6 tumor xenograft model, the NPs combined with free anti-CTLA-4 were able to decrease tumor mass by ~80%, in contrast to ~60% decrease without CTLA-4 antibody, and ~40% with nab-paclitaxel only." (PMID 38756653, 2024). "In fact, a previous study found that peptide vaccines combined with anti-CTLA-4 significantly reduced the proportion of intratumoral Tregs in the same TC-1 tumor model." (PMID 38459592, 2024). "Tumor-infiltrating Tregs (TI-Tregs), characterized by CD45RA− CD25hi Foxp3hi CTLA-4 hi phenotype, promote tumor evasion through various mechanisms." (PMID 39085965, 2024). "In LC, an immunoresistance mechanism adopted by tumor cells is the expression of immuno-inhibitory molecules in the tumor microenvironment such as PD-L1 and CTLA-4." (PMID 39199571, 2024). "Since ICIs like anti-CTLA-4 and anti-PD-1 prevent T cell depletion and maintain their anti-tumor effectiveness, the combination of RT and these agents has demonstrated great potential." (PMID 39044839, 2024). "By concurrently targeting NKG2A and the well-established modulator CTLA-4 in T cell responses, our aptamer seeks to augment the anti-tumor immune response, presenting a comprehensive approach to dual immune checkpoint blockade." (PMID 38473398, 2024). "Anti-CTLA-4 favors anti-tumor activity by blocking CD80-CTLA-4 binding which increases T-cell activation leading to clonal expansion." (PMID 39616333, 2024). "Intriguingly, anti-tumor activity was lost when anti-CD40 was eliminated together with either anti-CTLA-4 or CpG, while some anti-tumor activity was retained when the anti-CTLA-4 and CpG were both eliminated." (PMID 38731089, 2024). "The TCIA database enables the calculation of IPS from a tumor sample to predict the response to PD-1 and CTLA-4 inhibitors." (PMID 38900330, 2024). "Some studies have proposed that CD8+ T cells are involved in the anti-tumor effects of anti-CTLA-4 Abs and drug discovery targeting CD8+ T cells is progressing worldwide." (PMID 39106430, 2024). "In summary, TF is a promising natural small‐molecule compound for tumor immunotherapy, and when combined with an anti‐CTLA‐4 antibody, it shows a stronger ability to inhibit CRC cell growth, which in turn stimulates a more vigorous antitumor immune reaction." (PMID 38938284, 2024). "Seminal research has further demonstrated that the antibody blocking of CTLA4 can evoke robust immune responses, leading to tumor regression." (PMID 38617537, 2024). "Considering the importance of CTLA-4 in tumor development, the purpose of this meta-analysis was to comprehensively analyze published studies to further clarify the relationship between CTLA-4 gene polymorphisms and hematologic malignancy." (PMID 39464701, 2024). "Increased VISTA expression is observed on tumor-infiltrating macrophages, MDSCs, and tumor cells, with some exhibiting resistance to CTLA-4 and PD-1 blockade therapy." (PMID 38785789, 2024). "The immune checkpoint molecules, including cytotoxic T‐lymphocyte antigen‐4 (CTLA‐4) and programmed death receptor‐1 and its ligand (PD‐1/PD‐L1), play a significant role in facilitating immune evasion by tumor cells." (PMID 38566277, 2024). "A comprehensive analysis of a database comprising 290 iCCA patients, alongside tumor tissue immunohistochemistry, revealed that CTLA-4+ TILs and PD-L1+ TILs can independently predict tumor recurrence and OS in iCCA patients following surgical resection." (PMID 39845973, 2024). "The combination of hIL-7/mIL-12-VV with anti-PD-L1 or CTLA4 antibodies induced tumor regression via enhancing the CD8+ T cells and reducing the Tregs." (PMID 39451566, 2024). "A recent report demonstrated that, in mice, the irAEs associated with anti-CTLA-4 antibody treatment were mediated by the lysosomal degradation of CTLA-4 and that the avoidance of degradation led to more effective tumor rejection with fewer irAEs." (PMID 38312352, 2024).
tumor (continued). "Either Hsc70 overexpression or AUY-922 treatment can reduce PD-L1 expression, inhibit tumor growth and promote anti-tumor immunity in female mice; AUY-922 can further enhance the anti-tumor efficacy of anti-PD-L1 and anti-CTLA4 treatment." (PMID 38762492, 2024). "Inhibition of the interaction between CTLA4 and its ligands allows T cells to remain active and target and destroy tumor cells." (PMID 39198311, 2024). "CTLA4, through Cbl-b, inhibits the activity of key proteins such as PKCθ, Vav1, and PLCγ, leading to diminished anti-tumor immune responses by T cells." (PMID 39315102, 2024). "These 2 cell clusters were also co-expressing with activation markers (Pdcd1 and Ctla-4) and effector molecule (Gzmb an Ifng), suggesting the strong proliferative and anti-tumor activity." (PMID 38280084, 2024). "Blocking these receptors (e.g., PD-1 and CTLA-4) reverses the state and reactivates the immune response, thereby halting tumor progression 12, 41-44 which demonstrates the great potential of immune checkpoint blockade therapies in this regard." (PMID 38495503, 2024). "Allison and colleagues demonstrated that the application of CTLA-4 blocking antibodies resulted in complete tumor rejection and long-lasting immunity in mice due to a potentiated anti-tumor immune response." (PMID 38573347, 2024). "CTLA-4 inhibitors, such as ipilimumab, can enhance and prolong the adaptive immune response to tumor cells by blocking the CTLA-4 molecule." (PMID 39935851, 2024). "Overall, high abundance of CTLA4+ T cells and high levels of CTLA4 in tumor tissues contributed to the poor prognosis of HCC." (PMID 38604154, 2024). "Whereas CTLA-4 blockade stimulates the accumulation of 4PD-1hi cells in the tumor and periphery, PD-1 blockade opposes 4PD-1hi activity even in combination with anti-CTLA-4, thereby promoting a stronger antitumor immune response." (PMID 38333710, 2024). "We found that the Treg response in the TC-1 tumor model was enforced by RT and further promoted by CTLA-4 blockade." (PMID 38349740, 2024). "In the Phase I study of the bsAb KN046, targeting PD-L1 and CTLA-4, exploratory analyses of biomarkers were conducted in 93 patients with advanced solid tumors, evaluating tumor PD-L1 expression." (PMID 39068460, 2024). "Checkpoint blockade by anti-CTLA-4 antibodies increased velocities of antigen-specific T cells in tumor-draining lymph nodes." (PMID 39796680, 2024). "Several compounds inhibited tumor development prophylactically and therapeutically in syngeneic and CTLA–4–humanized mice." (PMID 38312352, 2024). "Important immunosuppressive molecules such as PD‐1 and CTLA‐4 enhance tumor incidence and growth by aiding in the evasion of immune surveillance." (PMID 37903487, 2024). "Immune checkpoint inhibitors such as anti-CTLA-4 and anti-PD-1/PD-L1 therapies are designed to enhance T-cell killing of tumor cells." (PMID 39682188, 2024). "Released DAMPs induce anti-tumor immune responses and synergise with anti-CTLA-4 antibodies to exert anti-tumor effects." (PMID 38853203, 2024). "In conclusion, studies on mouse models have shown that silencing METTL1 can inhibit tumor occurrence and development, increase mouse survival, and enhance the efficacy of immunotherapy targeting CTLA4 and PD1." (PMID 38693422, 2024). "Our results on gut microbial shift studies of APG‐157 + anti‐CTLA‐4 antibody treatment indicated that there is enhanced anti‐tumor immune response of the SCCVII H&N cancer cells possibly partly due to Lactobacillus." (PMID 38686626, 2024). "In 4T1 tumor-bearing mice, a combination of entinostat, anti-PD-1, and anti-CTLA-4 antibodies strengthened the antitumor effect and eradicated the tumor." (PMID 38898505, 2024). "Checkpoint inhibitors that block PD-1/PD-L1 or CTLA-4 interactions can reinvigorate exhausted T cells and allow for tumor recognition, restoring their cytotoxic functions." (PMID 39335494, 2024).
tumor (continued). "Combining peptide vaccines with immune checkpoint inhibitors, such as anti-PD-1/PD-L1 and anti-cytotoxic T-lymphocyte-associated protein 4 (CTLA-4) antibodies, has shown promising results by counteracting the immunosuppressive tumor microenvironment." (PMID 39204073, 2024). "The key ICIs in current use consist of monoclonal antibodies targeted to cytotoxic T lymphocyte antigen 4 (anti-CTLA4) and programmed cell death 1/ligand 1 (anti-PD-1/PD-L1), which is a key signaling molecule in immune escape pathways of tumor cells." (PMID 39559363, 2024). "In this study, using several tumor models, we show that an approach combining local RT, srIL-2, IL-12 and anti-CTLA-4, which we call a combined radio- immunotherapy (CRI) regimen, can eradicate tumors with volumes of 2,000 mm3 or larger." (PMID 39076988, 2024). "The IF double staining assay demonstrated that the CTLA4 level in the tumor tissues was mainly concentrated in tumor cells after anti-CD47 Ab treatment." (PMID 38398223, 2024). "These preclinical findings highlight the translational potential of CTLA-4 inhibiting aptamers in modulating the immune response within the tumor microenvironment." (PMID 38473398, 2024). "These agents target inhibitory immune pathways such as the PD-1/PD-L1 and CTLA-4 pathways, enabling the reactivation of exhausted T cells and restoring immune surveillance against tumor cells." (PMID 39682299, 2024). "Mice treated with neo VAX in combination with anti-CTLA-4 or anti-PD-1 displayed enhanced tumor control as compared to control VAX (irrelevant SLP + pI:C) + anti-PD-1 or control VAX + anti-CTLA-4." (PMID 38187708, 2024). "By binding to CTLA4 on target cells, anti-CTLA4 Ab engages FcRs on macrophages, generating “eat me” signals that trigger Ab-dependent cell-mediated phagocytosis—a significant mechanism contributing to the anti-tumor effects of CTLA4 Ab." (PMID 38398223, 2024). "The interaction between CSCs and immune cells, mediated by immune checkpoint molecules like PD-L1 and CTLA-4, underscores the importance of targeting these molecules in tumor immunotherapy." (PMID 39184916, 2024). "ICIs regulate T-cell activation by targeting PD-1, PD-L1, and CTLA-4 to enhance their anti-tumor capacities." (PMID 38291431, 2024). "Mice treated with PD‐1 and CTLA‐4 inhibitors showed significant reductions in tumor volume and body weight." (PMID 39001676, 2024). "In syngeneic tumor models, we observed that the combination of TU2218 and an anti-CTLA4 antibody not only induced tumor CR but also completely eradicated repeated tumor challenges through the formation of immunological memory." (PMID 39105882, 2024). "Studies have also leveraged PD-1/PD-L1 and CTLA4– targeting antibodies radiolabeled with 89Z for evaluating the tumor uptake of therapeutics using PET imaging; however, such measurements are associated with challenges." (PMID 39850874, 2024). "The interference of ipilimumab on CTLA-4 expressed on the subset of tumor-specific T-cell proliferation and B7 molecules on antigen-presenting cells is expected to prevent tumor development." (PMID 38410760, 2024). "By inhibiting CTLA-4, these drugs promote sustained T-cell activation and proliferation, leading to enhanced anti-tumor immune responses." (PMID 39127974, 2024). "This study showed that prior anti-CTLA-4 treatment modifies genomic and transcriptomic features predictive of anti-PD-1 response, highlighting differences in baseline melanoma tumours across immunotherapy trials." (PMID 39337605, 2024). "Analysis of MMRd tumors treated with a combination of anti-PD-1 and anti-CTLA-4 showed a role for γδ-T cells in targeting MMRd tumor cells with defective antigen presentation potentially via de NKG2D/NKG2DL ligand-receptor interaction." (PMID 39544936, 2024). "Within our experimental framework, mice engrafted with MC38 tumors were treated with either IgG or anti-CTLA4 antibodies, and we meticulously monitored changes in tumor volume." (PMID 39676867, 2024).
tumor (continued). "LAG-3 represents another promising treatment target after PD-L1 and CTLA-4; it induces T cell depletion and blocks T cell proliferation, preventing anti-tumor responses." (PMID 39397869, 2024). "To explore the effect of Foxp1 on the anti-CD47 Ab regulation of the CTLA4 level, we constructed a subcutaneous transplantation tumor model with Foxp1-deleted LLC cells and wild-type LLC cells, respectively, in mice, and treated them with anti-CD47 Ab." (PMID 38398223, 2024). "Let-7a/b overexpression in combination with anti CTLA-4 obtained the best results in terms of higher tumor lymphocyte infiltration and reduction in tumor volume." (PMID 38339019, 2024). "Ipilimumab, an FDA-approved inhibitor of CTLA-4, disrupts the B7-CD28 interaction by blocking CTLA-4, thereby boosting T cell immune responses against tumor cells." (PMID 39184916, 2024). "M2 macrophages inactivate CD8+ T and NK cells through the cluster of PD-L1, and Treg cells express cytotoxic T lymphocyte-associated protein 4 (CTLA-4), suppressing cytotoxic T cells for tumor clearance." (PMID 39263145, 2024). "They demonstrated tumor-specific radiopharmaceutical accumulation with increased uptake in tumors with higher CTLA-4 expression." (PMID 39104861, 2024). "By restricting immune checkpoint pathways such as the PD-1/PD-L1 and CTLA-4 pathways, the immunosuppressive microenvironment induced by tumor cells can be effectively weakened." (PMID 39408814, 2024). "blockade of CTLA-4 increases T cell activity and proliferation, including tumor-infiltrating effector T cells, and increases growth." (PMID 39136027, 2024). "We injected C57BL/6 mice with either 6694c2 EV or Mgat5-KO cells and treated tumor-bearing animals with a combination of PD-1– and CTLA4-blocking antibodies when tumors reached 50–100 mm3 in volume." (PMID 38912584, 2024). "Recent studies have shown dual blockade of PD-1 and CTLA-4 inhibitory pathways, remarkably enhances anti-tumor immune responses." (PMID 38234663, 2024). "With regard to ICIs, the modulation of cytotoxic T-lymphocyte-associated protein 4 (CTLA-4), programmed death cell protein 1 (PD-1)/programmed death ligand 1 (PD-L1), LAG3, B7-H3, and B7-H4 on CD8+ tumor-infiltrating lymphocytes (TILs) are the primary targets." (PMID 38398135, 2024). "The high MMrisk group was positively correlated with B cells, plasma cells, CD4 memory cells, Mast cells, CAFs, monocytes, M2 macrophages, Endothelial, tumor mutation, and most immune checkpoints (PD1, Tim-3, CTLA4, LAG3)." (PMID 38890346, 2024). "The antibodies represented by Ipilimumab, with CTLA-4 as the core, have greatly improved the efficacy of this type of tumor." (PMID 38979409, 2024). "Specifically, CTLA4 expression had a consistently high correlation within the tumor and stromal compartments and between the two compartments." (PMID 39769193, 2024). "HIF1-α is responsible for the upregulation of immunomodulatory surface ligands like cytotoxic T-lymphocyte-associated protein 4 (CTLA-4) and programmed death ligand 1 (PD-L1), causing the inhibition of the anti-tumor immune responses." (PMID 39409094, 2024). "Tumor cells can create immunological checkpoint molecules such as PD-L1 and CTLA-4 in response to hypoxia, which limits T cell activation and proliferation." (PMID 38200568, 2024). "Based on the results of risk analyses, clinical aspects of patients, biological aspects of the tumor, and survival of CM patients, we selected CTLA-4 c.-1577G>A as the SNV of greatest interest for this study, thus making it the object of functional analyses." (PMID 39596391, 2024). "Cytotoxic T lymphocyte-associated protein-4 (CTLA-4) has been found able to bind to TEX cells and blocking CTLA-4 with antibodies has been shown to enhance the anti-tumour immune response in mouse preclinical models." (PMID 38475858, 2024).